BCL9 (BCL9 transcription coactivator)
Diseases named in the same sentence as BCL9 in open-access papers (continued):
Sharing a sentence is not in itself a finding about the gene and the disease.
tumor (continued). "Importantly, T cell activation was enhanced in tumors and TdLNs from B16-OVA tumor-bearing Bcl9/Bcl9l deficiency mice." (PMID 38811552, 2024). "In addition, anti-PD-1 therapy achieved a greater decrease in MC38 tumor growth of Bcl9/Bcl9l deficiency mice than those of Bcl9f/fBcl9lf/f mice as well as increased the survival in Bcl9f/fBcl9lf/f Cre-ERT2 mice (TGI = 92.3%)." (PMID 38811552, 2024). "Loss of BCL9/9L accelerates differentiation and delayed tumour growth in APC or KRAS tumours." (PMID 35815339, 2022). "We studied the TME of CRC with single-cell sequencing and consequently found that Bcl9 depletion caused a pro-tumor effect of CAFs, while inhibition of abnormal activation of Wnt/β-catenin signal through Bcl9 depletion benefited T-cell–mediated antitumor immune responses." (PMID 34026600, 2021). "Considering the other genes with novel frequent frameshift mutations, BCL9 and PTCH1 mutations were also mostly heterozygous and truncal, although one tumor had a homozygous BCL9 mutation and both genes were found to have a subclonal mutation in one tumor each." (PMID 28539123, 2017). "Due to the critical role of BCL9 in promoting tumor development in the Wnt/β-catenin signaling pathway, the specific regulation of BCL9 expression by HIF1α is considered to be an underlying crosstalk between Wnt/β-catenin signaling and hypoxia signaling pathways." (PMID 28074862, 2017). "However, the BCL9 gene, mapped in the 1q21, plays an important role in the Wnt signaling pathway and it is associated with tumor progression." (PMID 25180186, 2014). "Thus, we presumed that in BCL9-mutated or amplified recurrent HCC (around 50% of recurrent tumor), combining targeting BCL9 and immune-checkpoint therapies may act as a novel therapeutic approach." (PMID 35078970, 2022). "Hence, the subtle changes in gene expression may underlie the modulatory role of Bcl9 and Bcl9L on β-catenin-mediated Wnt signaling and tumor progression (see “Discussion”)." (PMID 34545187, 2021). "Thus, Bcl9 loss essentially cures Apc1322T mice of their neoplastic disease." (PMID 30760710, 2019). "In vivo, Bcl9@TP treatment markedly reduced tumor burden, with a tumor growth inhibition (TGI) rate of ~62%, significantly higher than the control group." (PMID 40948801, 2025). "A pivotal contributor to this process is the binding of β-catenin to B-cell lymphoma 9 (BCL9), which promotes transcription of oncogenes and fosters an immune-suppressive tumor milieu." (PMID 40948801, 2025). "In the WNT/β-catenin signaling pathway, a high impact (premature stop codon) mutation (VAF = 0.010 in HCC cell line to VAF = 0.047 in HCC tumor) and missense mutation (VAF = 0.028 in HCC tumor) in BCL9 was identified." (PMID 40340757, 2025). "To further elucidate the mechanistic basis of Bcl9@TP’s antitumor activity, we conducted IHC analyses on tumor sections from each treatment group." (PMID 40948801, 2025). "As a result, Bcl9 depletion was suggested to attenuate inflammation driven by M0 and M1 macrophages while preventing the formation of tumor-promoting M2 macrophages." (PMID 40362354, 2025). "Staining for the proliferation marker Ki-67 revealed a significant reduction in tumor cell proliferation following Bcl9@TP monotherapy, with the Ki-67 index decreasing by approximately 55% compared to the control group." (PMID 40948801, 2025). "A tumor growth inhibition rate (TGI) of ~62% was attained with Bcl9@TP, reflecting its significant therapeutic activity." (PMID 40948801, 2025). "Suppressing B-cell lymphoma 9 and B-cell lymphoma 9-like (BCL9/BCL9L) inhibits tumor growth and boosts immune responses against cancer." (PMID 38811552, 2024). "Together, we demonstrate that targeting BCL9/BCL9L plays a crucial role in cDC1-modulated antigen presentation of tumor-derived antigens, as well as CD8+ T cell activation and tumor infiltration." (PMID 38811552, 2024).
tumor (continued). "The expression of phospho-TAK1, phospho-NF-κB p65, and IRF1 of intratumoral cDC1 were upregulated from hsBCL9z96-treated CT26 tumor-bearing mice, as well as from MC38 tumor-bearing Bcl9/Bcl9l deficiency mice." (PMID 38811552, 2024). "To investigate tumor growth driven by oncogenic BCL9, we developed a novel hsBCL9z96 that targets the BCL9/β-catenin interaction to inhibit the Wnt/β-catenin signaling pathway." (PMID 38811552, 2024). "CD8+ T cell in vitro proliferation was increased in cross-presentation of CD11c+ DC-CD8+ T cells in both hsBCL9Z96 tumor model and Bcl9/Bcl9l KO tumor model compared with vehicle and wild-type (WT) respectively." (PMID 38811552, 2024). "To further investigate how BCL9/BCL9L regulates the functions of cDC1, we explored the transcriptional differences of CD8+ T cells and cDC1 in TdLNs and tumors from B16-OVA tumor-bearing Bcl9/Bcl9l deficiency mice using single-cell transcriptomics analysis." (PMID 38811552, 2024). "Here, we report that inhibition or depletion of BCL9/BCL9L markedly restrained tumor growth and enhanced antitumor responses." (PMID 38811552, 2024). "We found that cDC1 numbers are increased in tumors from hsBCL9z96-treated CT26 tumor-bearing mice, as well as MC38 tumor-bearing Bcl9/Bcl9l deficiency mice." (PMID 38811552, 2024). "The mRNA and protein levels of the IFN-γ-induced chemokine CXCL9 were also upregulated in tumors from hsBCL9z96-treated CT26 tumor-bearing mice and MC38 tumor-bearing Bcl9/Bcl9l deficiency mice." (PMID 38811552, 2024). "AuNPs can successfully deliver β-catenin-BCL9 interaction-disrupting peptides into cancer cells to inhibit Wnt/β-catenin signaling and tumor growth with favorable biosafety and biocompatibility." (PMID 39065798, 2024). "Pharmacological inhibition of BCL9/BCL9L with a novel inhibitor hsBCL9z96 or Bcl9/Bcl9l knockout mice markedly delayed tumor growth and promoted antitumor CD8+ T cell responses." (PMID 38811552, 2024). "To precisely investigate how BCL9/BCL9L governs the functions of cDC1, we performed single-cell sequencing (scRNA-seq) of tumors and TdLNs from B16-OVA tumor-bearing Bcl9/Bcl9l deficiency mice." (PMID 38811552, 2024). "We found that XCL1 expression by intratumoral CD8+ T cells was upregulated in hsBCL9z96-treated CT26 tumor-bearing mice and MC38 tumor-bearing Bcl9/Bcl9l deficiency mice." (PMID 38811552, 2024). "BCL9/BCL9L binding to β-catenin can significantly affect tumor growth, suggesting that BCL9/BCL9L interacting with β-catenin plays a key role in tumor progression." (PMID 37868974, 2023). "The impact of BCL9 suppression on promoting CD155 expression by tumor cells was recently demonstrated, providing new insight into the role of BCL9 in regulating CD226 and CD96 immune receptors." (PMID 36717657, 2023). "BBI prevented the interaction of β-catenin and BCL9 in tumor cells, inhibited the activation of the canonical Wnt/β-catenin signaling pathway, thereby inhibiting the growth of tumor cells and recruiting more CD8+ T cells to act on the tumor." (PMID 37351175, 2023). "Targeting BCL9/BCL9L shows a direct anti-tumor effect, which involves anti-tumor immune responses through inhibiting Wnt and TGF-β signal transduction." (PMID 36918563, 2023). "BCL9/BCL9L inhibited the infiltration of CD8 + T cells in the tumor microenvironment, and promoted striple-negative breast cancer growth through the Wnt and TGF-βpathways." (PMID 37013637, 2023). "Some studies have shown that BCL9 antagonists can inhibit tumor growth, promote CD8+ T cell infiltration of tumors, and enhance anti-PD-1 immune responses." (PMID 37351175, 2023). "In a previous publication, an overexpression of transcription factor TCF7L2 and BCL9 was found, which is known to promote tumor progression by conferring enhanced proliferation, metastatic, and angiogenic properties to cancer cells." (PMID 37285354, 2023).
tumor (continued). "EEC-derived EXOs can inhibit B-cell CLL/lymphoma 9 (BCL9) expression by delivering miRNA-30c to block the Wnt/β-catenin signaling pathway, thereby attenuating the tumor-like behavior of ectopic endometrial epithelial cells (ecto-EECs) in EM." (PMID 37680720, 2023). "BCL9 is highly expressed in human tumor tissues, and β‐catenin/BCL9 is an important target for cancer treatment." (PMID 35229987, 2022). "Recently, a peptide drug, a protein–protein interaction inhibitor (PPI), that disrupts the β-catenin/Bcl9 interaction in the tumoral Wnt/β-catenin pathway has become a promising candidate drug for immune enhancement and tumor growth inhibition." (PMID 35745877, 2022). "Ultimately, this study proved that BCL9 inhibition altered cellular diversity within the tumor immune milieu and shed light on the role of BCL9 in regulating CD226 and CD96 checkpoints." (PMID 36032085, 2022). "miR-30c delivered by EECs-derived exosomes repressed BCL9 expression to block the Wnt/β-catenin signaling pathway, thus attenuating the tumor-like behaviors of ecto-EECs in EMs." (PMID 35368023, 2022). "As per our design, GdOFBAu conferred the ability to target tumors with the peptide Bcl9 and then selectively inhibited tumor cell proliferation and apoptosis by blocking the β-catenin/Bcl9 interaction." (PMID 35745877, 2022). "BCL9 then promotes tumor progression and tumor microenvironment (TME) remodeling by maintaining calcium transients and neurotransmitter-dependent communication between CRC cells." (PMID 35836256, 2022). "The results showed that BCL9 expression was up-regulated in the tumor samples, especially in the recurrent tumor samples, compared with that in adjacent non-tumor liver samples." (PMID 35078970, 2022). "We found that CD155/PVR-CD226 signaling occurs through VAV1 phosphorylation and BCL9 inhibition promotes antibody-mediated PD-1 blockade via promoting cytotoxic CD8+ T cell tumor infiltration in mouse models." (PMID 34417435, 2021). "Tumor-infiltrating T cells in Bcl9-shRNA compared to NT-shRNA bearing tumors exhibited pathways enriched for TLR, FOXP3, and IL-2." (PMID 34417435, 2021). "Interfering with the β-catenin-B9/B9L interactions with Bcl9/9L-ΔHD2 or β-catenin-D164A provoked a significant reduction in primary tumor growth, malignant tumor progression, and metastasis formation." (PMID 34545187, 2021). "In CT26 tumor cells group where Bcl9 was knocked down by shRNA, Rgs5, Dmkn, and Ass1 were highly expressed." (PMID 34026600, 2021). "Overall, it appears that Bcl9 depletion, either in tumor or stromal cells, not only reduces tumor growth, but also promotes infiltration of cytotoxic and effector CD8+ T cells." (PMID 34417435, 2021). "In summary, we found that BCL9 suppression reduced tumor growth, promoted CD8+ T cell tumor infiltration, and enhanced anti-PD-1 response." (PMID 34417435, 2021). "As expected, BCL9 expression in tumor tissues was markedly higher than that in normal tissues of CRC patients." (PMID 33838016, 2021). "The role of BCL9 in Treg cells was investigated using the Transwell migration method to simulate tumor infiltration by immune cells." (PMID 34417435, 2021). "Enrichment of CD8+ T and NK&T cells in tumor is upon BCL9 genetic depletion and pharmacological inhibition." (PMID 34417435, 2021). "Our analyses confirmed many important observations that were previously made by bulk sequencing, either in vitro or in animal models, and highlighted key areas for further studies of BCL9 in the tumor immune microenvironment." (PMID 34417435, 2021). "It was confirmed that disruption of the interaction between BCL9 and β‐catenin selectively inhibits oncogenic Wnt transcription, thereby suppressing tumor growth and metastasis in CRC." (PMID 33838016, 2021). "Bcl9/Bcl9L contribute to the initiation and maintenance of TGFβ-induced EMT and cell migration in vitro, yet the complete loss of Bcl9/Bcl9L has led to tumor cell apoptosis in vitro and in vivo." (PMID 34545187, 2021).
tumor (continued). "Motif gene sets a direct comparison of tumor cells between NT group and Bcl9 knockdown group revealed IK3, IRF pathway as the enriched signature in tumor cells." (PMID 34026600, 2021). "Here, we have dissected the roles of the interactions of Bcl9 and Bcl9L with Pygopus and with β-catenin during tumor progression and metastasis formation in the MMTV-PyMT mouse model of metastatic breast cancer." (PMID 34545187, 2021). "We applied SCENIC analysis to unravel which transcription factors determine differences in CT26 tumor cell expression between NT and Bcl9 KD tumor cells." (PMID 34026600, 2021). "Pharmacological inhibition of BCL9 reduces tumor infiltration by Treg cells due to inhibition of CCR4 expression." (PMID 34417435, 2021). "Tumor growth was significantly reduced in Bcl9-depleted tumors treated with anti-PD-1 antibody, compared to NT-shRNA tumors receiving anti-PD-1 alone, with a TGI of 81.8% by day 16, while in the MC38 model with MSI, anti-PD-1 therapy displayed a TGI of 56.72%." (PMID 34417435, 2021). "Here, we have analyzed the effect of interfering with the Bcl9/Bcl9L branch of Wnt signaling on tumor cell growth and invasion in a mouse model of metastatic breast cancer (FVB/N-Tg(MMTV-PyVT)634Mul/J)." (PMID 34545187, 2021). "In contrast, depletion of Bcl9 in CT26 tumor cells increased CD226+CD8+ T cell tumor infiltration accompanied by increased expression of Pvr/CD155." (PMID 34417435, 2021). "To investigate the heterogeneity of murine CT26 tumor treated with hsBCL9CT-24 and genetically depleted Bcl9, we conducted single-cell mRNA sequencing in 12 samples." (PMID 34566638, 2021). "Increased mRNA levels of Gli1 and Ptch1 were seen in hsBCL9CT-24 or Bcl9-shRNA treated CT26 tumor cells, suggesting that BCL9 suppression activates CD155 expression via sonic hedgehog signaling." (PMID 34417435, 2021). "Six tumor samples were operated (B18, NT-shRNA sample 18; B19, NT-shRNA sample 19; B22, NT-shRNA sample 22; B24, BCL9-shRNA sample 24; B25, BCL9-shRNA sample 25; and B29, BCL9-shRNA sample 29)." (PMID 34026600, 2021). "The impairment of β-catenin binding to Bcl9/Bcl9L also significantly reduced tumor progression and lung metastasis formation." (PMID 34545187, 2021). "In this study, we explored the involvement of Wnt signaling in the tumor immune microenvironment (TIME) by assessing how inactivation of BCL9, which acts as a necessary co-factor of β-cat, affects the activity of tumor infiltrating T cells." (PMID 34417435, 2021). "For CRC, knockdown of BCL9 or blocking the interaction between BCL9 and β‐catenin inhibits tumor growth, angiogenesis, and metastasis." (PMID 33838016, 2021). "BCL9 subsequently promotes tumor progression and remodeling of the tumor microenvironment (TME) by sustaining the calcium transients and neurotransmitter-dependent communication among CRC cells." (PMID 31911584, 2020). "In order to study the effect of BCL9 dysfunction on tumor single cell at mRNA levels, we grouped and integrated the BCL9 Genetic deprivation and inhibitor-treated single-cell mRNA sequencing data to remove the batch effect." (PMID 33552975, 2020). "In the virtual time analysis of the endothelial cell population, it can be seen that BCL9-endo-Score and the traditional signal pathway “angiogenesis” have a certain overlap in the development of tumor endothelial cells." (PMID 33552975, 2020). "MiRNA-122 has been found to target a number of genes linked with tumour progression, including Snail 1 and Snail 2, WNT1, CREB1, and BCL9." (PMID 31979312, 2020). "A study demonstrated that BCL9 knockdown reduced angiogenesis through down-regulation of vascular endothelial growth factor expressed by tumor cells." (PMID 33552975, 2020). "It is reported that peptides targeting BCL9/9l prevent tumor development and inhibit Wnt/β-catenin pathway activity in multiple CRC models." (PMID 33552975, 2020).
tumor (continued). "Our BCL9 and/or BCL9L knockdown experiments underline the possible advantageous effect of downregulation of BCL9 proteins on tumor growth control." (PMID 31440992, 2020). "In functional studies, shRNA-mediated knockdown of BCL9 in HMCLs suppressed Wnt signaling and attenuated tumor growth in vitro and in vivo." (PMID 30770859, 2019). "This would explain why far fewer genes were differentially expressed in Pygo-deleted compared to Bcl9-deleted tumours." (PMID 30760710, 2019). "Intestinal deletion of Bcl9 extends disease-free survival in both models, and essentially cures Apc1322T mice of their neoplasia." (PMID 30760710, 2019). "Deletion of Bcl9 and Pygo extends the disease-free life in both models, especially deletion of Bcl9 which essentially cures Apc1322T mice of their neoplastic disease, restoring a normal life span in these otherwise moribund mice." (PMID 30760710, 2019). "After it was revealed that TRAF3 plays a powerful B cell-specific role in restraint of homeostatic survival, it has become evident that this TRAF3 role renders it an important tumor suppressor for B cell malignancies, particularly MM and BCL9." (PMID 31501481, 2019). "The knockdown of BCL9 expression increased survival rate in a nude mouse cancer cell xenograft model, reduced vascular formation in transplanted tumors, and inhibited tumor metastasis." (PMID 31827404, 2019). "Two conclusions can be drawn: firstly, a large fraction of the Bcl9- and Pygo-regulated genes are downstream of Apc, consistent with Bcl9 and Pygo acting predominantly on Apc-regulated genes in these tumours." (PMID 30760710, 2019). "Tumours were uniformly distributed between the proximal and distal SI in Cre-induced VillinCreERApcfl/+ mice, while upon deletion of Bcl9/9l there was a significant increase in the number of proximal intestinal tumours." (PMID 30760720, 2019). "A follow-up study in 2014 identified the oncogenic BCL9 as a direct target of the tumor suppressor microRNA miR-30-5p." (PMID 29776381, 2018). "BCL9 is a newly discovered pro-oncogene in the Wnt/β-catenin signaling pathway, and its abnormal expression is a new mechanism of tumor development." (PMID 28769030, 2017). "In vitro evidence from xenograft models indicated that BCL9 promoter/gene knockout inhibited HCC tumor growth and angiogenesis." (PMID 28074862, 2017). "The same is true for the APC tumor suppressor (>29x), a BCL9-specific hit that is recruited to TCF target genes upon Wnt signaling by β-catenin, owing to direct high-affinity binding." (PMID 28296634, 2017). "Similar to our study, delayed tumor development following chemical induction was also observed in Bcl9/Bcl9-2 double mutants." (PMID 27811361, 2016). "We have analyzed in our tumor models the expression of all four members of the Pyogous and Bcl9 co-factor families." (PMID 27811361, 2016). "miR-30 family members have been reported to function as tumor suppressors by inhibiting cell proliferation, invasion and inducing apoptosis through different mechanisms, such as targeting BCL9 and repressing Wnt signaling." (PMID 27199283, 2016). "BCL9 is involved in signal transduction through the Wnt pathway and is known to promote tumour progression." (PMID 25148247, 2014). "MiR-30c was previously reported to play a suppression role in tumour cell proliferation, metastasis and drug resistance by targeting BCL9, TWF1, vimentin and KRAS." (PMID 24595016, 2014). "They confirmed that Bcl9 KD reduces tumor growth and enhances CD8+ T-cell infiltration." (PMID 40362354, 2025). "Tumor weight measurements revealed a marked reduction in tumor burden in both the Bcl9@TP alone group and combination (Bcl9@TP + anti-PD-1) group compared to the control and anti-PD-1 groups, with the combination group exhibiting the most pronounced effect—an approximate 85% decrease in tumor mass." (PMID 40948801, 2025).